CLCA1 (chloride channel accessory 1)
Diseases named in the same sentence as CLCA1 in open-access papers (continued):
Sharing a sentence is not in itself a finding about the gene and the disease.
asthma (continued). "Asthma subjects were stratified into two subgroups, Th2-high, and Th2-low asthma, based on their expression of a three-gene signature of Type 2 inflammation: POSTN, SERPINB2, and CLCA1." (PMID 34088958, 2021). "Both the six gene signature (6GS: CPA3, DNASE1L3, CLC, IL1B, ALPL, and CXCR2) and T‐helper 2 signature (TH2S: CLCA1, SERPINB2, and POSTN) are proposed as biomarkers in the identification of inflammatory phenotypes of asthma in induced sputum and epithelial brushings, respectively." (PMID 31903716, 2020). "HEKs were chosen because they do not express some of the genes upregulated in asthma (CLCA1, POSTN, SERPINB2) and as such mirror expression of healthy BECs." (PMID 33362848, 2020). "CLCA1 is an IL-4 and IL-13 inducible, STAT6-dependent mediator of chloride ion transport/fluid production and mucin/mucus production and is involved in asthma." (PMID 32431691, 2020). "Most current research focuses on the function of CLCA1 in the airways where it is normally virtually absent but is up-regulated in diseases such as asthma and COPD." (PMID 31570526, 2019). "CLCA1 can directly modify TMEM16A activity, increase currents, influence the physiology of multiple tissues and the pathology of multiple diseases including asthma, COPD, cystic fibrosis, and certain cancers." (PMID 29463274, 2018). "Module M31 included the IL-13 response gene, CLCA1 and the mast cell marker carboxypeptidase A3 (CPA3), suggesting a greater expression of mast cell secreted proteases in peripheral airways compared to central airways in severe asthma." (PMID 28045928, 2017). "The present study adds to an accumulating body of evidence from gene-array studies that genes such as CLCA1, SerpineB2, MUC5AC, AGR2, CPA3, and tryptase are overexpressed in asthma, and suggests that these genes are more transcriptionally active in the EIB phenotype." (PMID 20052409, 2010). "Therefore, CLCA1 is considered to have an important role in respiratory diseases; however, its role in pediatric asthma has not been elucidated." (PMID 36313877, 2022). "Th2-high asthma has three specific differentially expressed transcriptomic profiles, namely, periostin (POSTN), chloride channel regulator 1 (CLCA1), and serpin peptidase inhibitor, clade B, member 2 (SERPINB2), among which POSTN was found to be a more reliable surrogate marker for Th2-high asthma." (PMID 35406434, 2022). "The observation that CS markedly reduces IL‐13‐induced CLCA1 and POSTN expression, which does not recover after CS cessation, is an important finding for biomarker‐guided therapy in asthma since especially periostin is considered as an emerging biomarker for Th2 inflammation." (PMID 28701525, 2017).
colorectal cancer (20 papers, 2013 to 2026). A primary or metastatic malignant neoplasm that affects the colon or rectum. "Increased expression levels of CLCA1 in colorectal cancer suppress growth and metastasis via inhibition of the Wnt/β-catenin signaling pathway in vitro and in vivo, whereas inhibition of CLCA1 causes the opposite results." (PMID 38203460, 2023). "Low expression level of CLCA1 was observed to be linked to poor prognosis in colorectal cancer and CLCA1 itself has been proposed as a prognostic marker." (PMID 29515771, 2018). "The down expression of five genes (SLC26A3, GUCA2A, CLCA4, CLCA1, and AQP8) was significantly associated with poor overall survival in colorectal cancer adenocarcinoma patients, and patients with lower expression levels of CLCA1 had poorer disease-free survival rates." (PMID 35693937, 2022). "CLCA1 may contribute to the increased spontaneous differentiation and reduced cell proliferation of colorectal cancer, and is thus associated with favorable prognosis of colorectal cancer patients." (PMID 29190973, 2017). "For example, the expression levels of CLCA1, which is one of the Ca2+-dependent Cl− channels, are significantly lower in colorectal cancer tissues than in normal tissues." (PMID 38203460, 2023). "Yang found that patients with colorectal cancer CRC had low expression of CLCA1 and CLCA4, and further experiments confirmed that CLCA1 is involved in tumor proliferation and invasion." (PMID 32797167, 2020). "In accordance with the expected results, the expression of CLCA1 protein was down-regulated in colorectal cancer tissues." (PMID 33251137, 2020). "Second, validation in GEO datasets is not ideal and pure bioinformatics analysis cannot well prove the prognostic significance of CLCA1 in colorectal cancer, in future research we will focus on large-scale population for further investigation." (PMID 33251137, 2020). "Several studies have reported that the CLCA1 expression is down-regulated in colorectal cancer tissues compared with adjacent normal tissues, with low CLCA1 expression predicting worse outcomes." (PMID 30419838, 2018). "It has been reported that CLCA1 can regulate the differentiation of colorectal cancer cells and function as a prognostic marker in colorectal cancer." (PMID 30419838, 2018). "This study was conducted to investigate the functions and mechanisms of CLCA1 in colorectal cancer (CRC)." (PMID 28974231, 2017). "CLCA1 plays a role in tumor suppression and has been shown to have a down-regulated expression in colorectal cancer." (PMID 28458684, 2017). "Researchers have observed significantly lower expression of CLCA1 in colorectal cancer tissues compared with normal tissues." (PMID 27661117, 2016). "Similarly, calcium‐activated chloride channel regulator 1 (Clca1) is consistently upregulated in naïve Lgmn−/− colon tissue and has been identified as a tumor suppressor in colorectal cancer." (PMID 40970443, 2025). "Elevated CLCA1 expression levels can inhibit the invasiveness of colorectal cancer (CRC)." (PMID 38612764, 2024). "CLCA1 could inhibit the proliferation of colorectal cancer cells, which is correlated with beneficial prognosis of colorectal cancer patients." (PMID 30312171, 2018). "Additionally, low expression of CLCA1 predicts tumor recurrence and poor survival in colorectal cancer patients." (PMID 29190973, 2017). "However, the biological functions and molecular mechanisms of CLCA1 in colorectal cancer (CRC) remain to be elucidated." (PMID 28974231, 2017). "As a second possible function it has been suggested that CLCA1 may play a role in the differentiation and proliferation of intestinal epithelial cells and colorectal cancer cells." (PMID 26162072, 2015).
colorectal cancer (continued). "Further in-vitro experiments suggested that CLCA1 may function as a tumor suppressor in colorectal cancer by inhibiting the Wnt/beta-catenin signaling pathway and epithelial-mesenchymal transition, while in-vivo overexpression of CLCA1 led to inhibition of proliferation and metastasis." (PMID 30419838, 2018). "Previous studies have shown that the increase of CLCA1 and CLCA4 levels in tumor tissue is related to the excellent prognosis of colorectal cancer patients, consistent with our survival analysis." (PMID 35693937, 2022). "Our data showed that CLCA1 and CLCA4 were significantly downregulated in colorectal cancer compared with normal tissues." (PMID 35693937, 2022). "Chloride Channel Accessory 1 (CLCA1) is a tumor suppressor protein that regulates differentiation and proliferation of colorectal cancer cells." (PMID 31337362, 2019). "Calcium-activated chloride channels (CLCAs) also are expressed in bovine, mouse and human enterocytes and there is an inverse correlation between the levels of chloride channel (CLCA1 and CLCA2) expression and tumorigenicity, indicating that they act as suppressors of breast and colorectal cancer." (PMID 23593331, 2013). "Here, we compared CLCA1 expressional levels between patients with and without colorectal cancer (CRC) and determined the functional role of CLCA1 in differentiation and proliferation of Caco-2 cells." (PMID 23593331, 2013).
cystic fibrosis (16 papers, 2014 to 2023). Autosomal recessive disorder caused by pathogenic variants in the CFTR gene (cystic fibrosis transmembrane conductance regulator), which encodes a chloride and bicarbonate channel expressed in epithelial cells, and follow the diagnosis criteria. "The secreted, goblet cell-derived protein Clca1 (chloride channel regulator, calcium-activated-1) has been linked to diseases with mucus overproduction, including asthma and cystic fibrosis." (PMID 26162072, 2015). "CLCA1 plays an essential role in goblet cell mucus production and innate immunity of respiratory and gastrointestinal diseases such as cystic fibrosis, ulcerative colitis, and gastrointestinal parasitic infection." (PMID 34784295, 2022). "Additionally, recent studies have indicated that CLCA1 does not play a role in calcium-activated chloride secretion in the respiratory tract nor does restoration of reduced Clca1 expression rectify the cystic fibrosis electrophysiology defect in the intestine." (PMID 26855614, 2016).
colon cancer (7 papers, 2013 to 2023). "Loss of CLCA1 expression prevents enterocyte differentiation and may promote colonic cancer progression." (PMID 31871532, 2019). "Loss of CLCA1 expression inhibits enterocyte differentiation and may lead to colonic cancer development." (PMID 23593331, 2013). "We found three candidate core, tumour, suppressor genes in colon cancer, namely, CLCA1, B3GNT6 and UGT2A3." (PMID 36855796, 2023). "CLCA1 expression was closely correlated with Th17 (rho=0.379, P=3.71e-19) levels in colon cancer and with Act-B (rho=0.419, P=2.46e-08), ImmB (rho=0.365, P=1.5e-06), neutrophil (rho=0.414, P=3.68e-08), and Th17 (rho=0.517, P<2.2e-16) levels in rectal cancer." (PMID 33251137, 2020). "Similar subpopulations have been described for the protein level of Chloride channel accessory 1 (CLCA1) and topoisomerase-1 (Topo1) in colon cancer patients, leading to different prognostic Outcomes." (PMID 26188124, 2015). "CLCA4 and CLCA1 are both expressed at highest levels in colon, and both are dramatically downregulated in colon cancer." (PMID 24386311, 2013). "In colon cancer, we observed the simultaneous low expressions of chloride channel accessory 1 (CLCA1), UDP‐GlcNAc:betaGal beta‐1,3‐N‐acetylglucosaminyltransferase 6 (B3GNT6) and UDP glucuronosyltransferase family 2 member A3 (UGT2A3), which indicated an favourable prognosis." (PMID 36855796, 2023). "Then, we analysed the expressions of CLCA1, UGT2A3 and B3GNT6 in 480 cases of colon cancer and 41 cases of adjacent tissues in the TCGA database and their effects on survival and metastasis." (PMID 36855796, 2023). "After repressing miR‐590‐3p with G4‐CSSD590, the upregulation of CLCA1, B3GNT6 and UGT2A3 inhibited the proliferation and metastasis of colon cancer cells." (PMID 36855796, 2023). "To verify the role of CLCA1, B3GNT6 and UGT2A3 in colon cancer, we overexpressed these genes in HCT‐116 and Caco‐2 colon cancer cells and tested their cell phenotype, proliferation, migration and invasion ability." (PMID 36855796, 2023). "The curves present survival data for the two groups of colon cancer patients based on gene expression level (high or low) of SPINK4, RETNLB, ASRGL1, CLCA1, and FCGBP (rows)." (PMID 31337362, 2019). "To confirm whether G4‐CSSD590 can restore the expression of CLCA1, UGT2A3 and B3GNT6 and its role in colon cancer after the adsorption of miR‐590‐3p, we transfected Ctrl CSSD, CSSD590 and G4‐CSSD590 in HCT116 and Caco‐2 cells." (PMID 36855796, 2023).
colitis (6 papers, 2016 to 2025). Inflammation of the colon. "CLCA1 also maintains mucus homeostasis to decrease the risk of colitis." (PMID 35893911, 2022). "In an attempt to investigate this protein in colitis, a series of studies negated the involvement of CLCA1 in gut inflammation until recently by using ex vivo assays." (PMID 38593125, 2024). "Mechanistically, Rab7 maintained optimal CLCA1 levels by controlling its lysosomal degradation, a process that was dysregulated during colitis." (PMID 38593125, 2024). "Rab7 downregulation, as observed during colitis, results in increased CLCA1 in goblet cell and thereby a higher secretion." (PMID 38593125, 2024). "Studies have shown that CLCA1 plays an important role in a mouse model of dextran sulfate sodium-induced colitis by the modulation of early immune responses through altered cytokine secretion." (PMID 36313877, 2022). "Here, we analyze the role of CLCA1, which is highly expressed and secreted by colon goblet cells, in the course of murine dextran sodium sulfate-induced colitis." (PMID 26855614, 2016). "In light of the absence of such possibly interfering effects, we postulated that possible differences in inflammatory parameters during DSS colitis in the Clca1-/- model would be due to primary CLCA1 effects on the immune response." (PMID 26855614, 2016). "In a previous DSS colitis study, we failed to observe any effects of Clca1-deficiency on mucus barrier integrity and mucin gene expression which likely would have affected secondary immune responses." (PMID 26855614, 2016). "Lack of CLCA1 was associated with a more than two-fold increased expression of Cxcl-1- and Il-17-mRNA during DSS colitis." (PMID 26855614, 2016).
nematode infection (5 papers, 2011 to 2025). "Hence, the expression of genes such as ITLN2, CLCA1, galectin 14, etc. appear to be consistently affected by nematode infection, in both lambs and adult sheep." (PMID 29703268, 2018). "The CLCA1 gene was upregulated in FUN and PYL, especially in FUN at 21 dpi, consistent with being one of a collection of inflammation-related genes elicited by nematode infection." (PMID 40076885, 2025). "While CLCA1 is not essential in the steady state to form a functional mucus barrier, it is crucial during nematode infections." (PMID 37869014, 2023).
ulcerative colitis (5 papers, 2019 to 2025). An inflammatory bowel disease involving the mucosal surface of the large intestine and rectum. "In mucus hypersecretory-related GI diseases, CLCA1 participates in the pathogenesis of colon colitis, ulcerative colitis, and GI parasite infections." (PMID 40076885, 2025). "In another study of the transition from ulcerative colitis to ulcerative colitis-associated colorectal cancer, the role of DPEP1, CD74, and CLCA1 in the progression of the disease was identified." (PMID 38339232, 2024). "(B) RT-PCR analysis of relative fold expression of CLCA1 gene in human ulcerative colitis (UC) (n = 22) patient colonic biopsies relative to average control (n = 22) values." (PMID 38593125, 2024).
pneumonia (4 papers, 2018 to 2022). An acute, acute and chronic, or chronic inflammation focally or diffusely affecting the lung parenchyma, caused by an infection in one or both of the lungs (by bacteria, viruses, fungi, or mycoplasma.). "For example, deficiency of CLCA1 in a mouse model of acute pneumonia resulted in reduced cytokine expression with less leukocyte recruitment and the human CLCA1 was shown to be capable of activating macrophages in vitro." (PMID 29610986, 2018). "Furthermore, CLCA1 deficiency resulted in decreased cytokine expression and decreased leukocyte recruitment in an acute pneumonia mouse model." (PMID 36313877, 2022). "The main phenotype of Clca1−/− mice in a model of S. aureus-induced pneumonia consisted of reduced activation of CXCL-1 and IL-17A expression and decreased neutrophilic infiltration into the bronchoalveolar space." (PMID 29610986, 2018).
gastric cancer (3 papers, 2016 to 2019). A primary or metastatic malignant neoplasm involving the stomach. "Studies have shown CLCA1 downregulation in CRC and ADH1C downregulation in gastric cancer." (PMID 31211760, 2019). "Among the top 10 DRGs for Chinese (GSE54129), six genes have been reported to be gastric cancer (GC) related (REG4, ANXA13, C7, ASS1, MSMB, CREB1) and the rest four were directly regulated by known gastric cancer genes in our GRNs, in which two genes are also cancer related (BPTF, CLCA1)." (PMID 29745833, 2018).
ovarian carcinoma (3 papers, 2016 to 2022). A malignant neoplasm originating from the surface ovarian epithelium. "Yet, evidence from ovarian cancer analysis revealed that CLCA1 was overexpressed during cancer progression, as determined by both RT-PCR and immunoblot analyses." (PMID 31871532, 2019). "Also, Calcium-Activated Chloride Channel Regulator 1 (CLCA1) was revealed to be overexpressed in ovarian cancer cell." (PMID 27825122, 2016).
staphylococcus aureus pneumonia (3 papers, 2014 to 2018). An pneumonia caused by infection with Staphylococcus aureus. "Furthermore, evidence from an in vivo Staphylococcus aureus pneumonia mouse model suggests that CLCA1 may also modify BPIFA1 expression in airway epithelial cells." (PMID 29610986, 2018). "In the respiratory tract, Clca1-/- mice develop decreased levels of Cxcl-1, a potent neutrophil chemoattractant, and of Il-17, a proinflammatory cytokine at the mRNA and protein levels with a consequent decrease in neutrophil response during Staphylococcus aureus pneumonia." (PMID 26162072, 2015).
adenoma (2 papers, 2019 to 2023). A neoplasm arising from the epithelium. "In cancer-adenoma, we found downregulation of CLCA1, which encodes a chloride channel expressed in intestinal goblet cells." (PMID 31211760, 2019). "For the adenoma–adenoma comparison made in the reference article, the CLCA1 and ADH1C genes were downregulated." (PMID 37565794, 2023). "In the adenoma-adenoma comparison, downregulation of several DEGs (CLCA1, ADH1C, ANXA10) in FAP case adenomas was observed." (PMID 31211760, 2019). "In this study, CLCA1 and ADH1C are downregulated in cancer compared to adenoma and in adenoma from FAP cases compared to FAP controls, indicating that downregulation of these DEGs within adenomas may indicate increased likelihood of neoplastic progression." (PMID 31211760, 2019).
allergic asthma (2 papers, 2021 to 2022). A asthma with a basis in a pathological type I hypersensitivity reaction. "CLCA1 is a regulator of mucus production in goblet cells, but studies describing its role in allergic asthma have been contradictory." (PMID 36324676, 2022). "MUC5B, ORMDL3, MUC5AC, CHI3L1, CLCA1, and IL-33 display a distinctly high non-specific relationship with allergic and non-allergic asthma." (PMID 33936056, 2021).
breast carcinoma (2 papers, 2011 to 2022). "CLCA2 that shares 63% sequence similarity with CLCA1 has been suggested to be a breast cancer tumor-suppressor gene." (PMID 21542898, 2011).
helminth infection (2 papers, 2020 to 2023). "Ang4, Clca1, and Retnlb are goblet-cell associated genes that are induced during immune responses, such as bacterial and helminth infections, and are typically stimulated by type 2 and 3 immune cytokines such as IL-4/IL-13 (type 2) and IL-22 (type 3)." (PMID 37869014, 2023).
lymph node metastases (2 papers, 2022 to 2023). "Three survival-related genes (TMEM59L, CLCA1, and TUBB2B) were associated with the lymph node metastasis and survival time of patients." (PMID 37719786, 2023). "CLCA1 protein expression was lower in the lymph node metastasis group, while the TMEM59L and TUBB2B were higher in the lymph node metastasis group." (PMID 37719786, 2023). "In this study, nine lymph node metastasis genes were analyzed via uni-factor COX regression, and three survival-related genes (TMEM59L, CLCA1, and TUBB2B) were ultimately identified." (PMID 37719786, 2023). "A uni-factor COX analysis was performed on the characteristic genes of lymph node metastasis, and three survival-related genes (p < 0.05) were obtained, including TMEM59L, CLCA1, and TUBB2B." (PMID 37719786, 2023). "In light of these observations and analysis in TCGA data, we hypothesized that TMEM59L, CLCA1, and TUBB2B may be the disease markers for lymph node metastasis of CRC." (PMID 37719786, 2023).